IL2 (interleukin 2)
Diseases named in the same sentence as IL2 in open-access papers (continued):
Sharing a sentence is not in itself a finding about the gene and the disease.
colitis (continued). "This is in agreement with studies in the Il2-/- mouse model, where increased expression levels of Reg3b and Reg3g genes might be associated with prevention of colitis triggered by colonization with commensal E. coli." (PMID 20630110, 2010). "Since the phenotype of mice with deficient IL-2-system almost perfectly matches the colitis observed in cattle with MCF, we suggest that OvHV-2-linked low abundance of IL-2 transcripts may be a key to further study the pathogenesis of MCF." (PMID 19603070, 2009). "plantarum Q7 (LpQ7-MVs) were administered to DSS-induced colitis mice, evidenced by the amelioration in the colonic histological damage, which was associated with the downregulation in the production and release of pro-inflammatory cytokines (IL-6, IL-1β, IL-2 and TNF-α)." (PMID 36558455, 2022). "Thus, these protective roles of low-dose IL-2 may mediate its treatment effects on DSS-induced colitis by inhibiting the loss of junctional molecules and reducing intestinal epithelial apoptosis in damaged intestinal tissue." (PMID 32308767, 2020). "In these mice, colitis is associated with expansion of T helper type 1 (Th1) and Th17 cell populations and a decrease in the number of FoxP3+ regulatory T (Treg) cells, and the pathology is linked to the inability of intestinal Cnb1-deficient CD11chighMHCII+ cells to express IL-2." (PMID 29549257, 2018). "In contrast, hippocampal homogenates revealed increased IL‐2 and IL‐6 cytokine levels following acute colitis." (PMID 40457749, 2025). "Another study employed a combination of an IL-2/IL-2 agonist immunocomplex with IL-5RA antagonist in the DSS colitis model, showing superior therapeutic efficacy compared to using the blocking IL-2/IL-2 agonist immunocomplex alone." (PMID 40475764, 2025). "exploit siderophores as an iron source, leading to extensive proliferation in Lcn10−/−/Il10−/− mice and inducing colitis and right-sided tumors when transferred to Il2−/− mice." (PMID 39051782, 2024). "Colitis is intestinal tissue inflammation, and IL-2 is a cytokine promoting the inflammatory response." (PMID 38790796, 2024). "In colitis, immune cells produce a considerable amount of IL-2 in response to inflammation, exacerbating the inflammatory response." (PMID 38790796, 2024). "Here, we evaluated the effects of Raf on inflammation using a DSS-induced colitis mouse model, focusing on serum levels of IL-2, IL-1β, TNF-α, and IL-6." (PMID 38928791, 2024). "Perilla seed oil, rich in α-linolenic acid, reduces colitis by suppressing inflammatory markers including interleukin-1 (IL-1), interleukin-2 (IL-2), interleukin-4 (IL-4), interleukin-5 (IL-5), interleukin-6 (IL-6), and interleukin-10 (IL-10)." (PMID 39022021, 2024). "LP-HFY11 lowered the interleukin-10 (IL-10) level and increased the IL-2 level in the serum of colitis mice." (PMID 38790796, 2024). "Together, this suggests a potential regulatory role of USP28 in modulating IL22 and IFNγ expression during acute DSS-induced colitis, with implications for the involvement of the IL2 pathway in this context." (PMID 39076972, 2024). "Treatment with MV significantly reduced the releases of proinflammatory factors TNF-α, IL-1β, and increased the levels of anti-inflammatory factors IL-2 in mice with colitis, indicating its good anti-inflammatory effects." (PMID 38773576, 2024). "Although IL-2 expression was not directly repressed by tofacitinib in vitro, the heightened frequency of IL-2+ T cells in colitis-diseased mice was partly controlled by later, but less so by earlier, tofacitinib administration." (PMID 37275854, 2023). "PS attenuated the severity of colitis by reducing IL-2 and IL-6 and shifted the IM composition toward a healthier profile, increasing the concentration of Bifidobacterium and reducing the concentration of harmful bacteria in the gut." (PMID 37190329, 2023).
colitis (continued). "L. bulgaricus and S. thermophilus in yogurt alleviated the symptoms of colitis in mice and induced IL-2 and IL-4 production in the lymph nodes and spleen, resulting in modulated helper T cells." (PMID 36986118, 2023). "This beneficial effect was reported to be mediated through the inhibition of TLR4-NF-κB-NLRP3 axis and, consistently, the pro-inflammatory cytokines (tumoral necrosis factor-α (TNF-α), IL-1β, IL-6, IL-2) levels were also suppressed in the treated colitis mice." (PMID 36558455, 2022). "Usual side effects from HD IL-2-included colitis, renal insufficiency, shortness of breath, electrolyte issues, hepatitis, and mucositis all resolving to grade 1 or better at the time of dismissal from the hospital." (PMID 36045435, 2022). "Consistently, low-dose IL-2 treatment alleviates DSS-induced colitis largely by inhibiting apoptosis and recovering intestinal integrity." (PMID 36614012, 2022). "The protective role of ILC3 during colitis is founded on their ability to express IL2, MHC class II (MHCII), and OX40L, which is relevant for their effect on T cell responses [4., 5., 6.,55., 56., 57.]." (PMID 35618586, 2022). "Our study found a significant increase in colonic expression of IL-17A, as well as IFNγ and IL-2, during colitis in mPGES-1−/− mice compared with WT mice." (PMID 34983695, 2022). "Ginseng polysaccharides were demonstrated to alleviate colitis symptoms in rats, accompanied by the downregulation of inflammatory cytokines (IL-1β, IL-2, IL-6, and IL-17)." (PMID 35745651, 2022). "DSS treatment induces Th17 cytokines (such as IL-17A) and Th1 cytokines (including IFNγ and IL-2) in the colon, and these cytokines are essential for developing colitis." (PMID 34983695, 2022). "TNF-α, IL-6, IL-1β, and IL-2 are involved in many inflammatory visceral pain diseases like visceral pain after colitis, surgery, and endometriosis." (PMID 35642022, 2022). "It has been shown that inflammatory phenotypes (such as colitis) are similar in IL-2−/− and IL-2Rα−/− mice." (PMID 35055297, 2022). "Transfer of an IL-2–tuned microbiota by FMT protected C57BL/6J mice from dextran sulfate sodium–induced colitis and prevented diabetes in NOD mice." (PMID 35917175, 2022). "Infusion of IL-2/anti-IL-2 complexes increased both IL-2 half-life and Treg numbers, along with suppressing murine diabetes, colitis, and skin allograft rejection." (PMID 35967386, 2022). "Therapy was held due to colitis and shortness of breath, with atrial fibrillation after dosing that resolved in a few days per usual after stopping HD IL-2." (PMID 36045435, 2022). "blossom, and then further determine the effect of these flavonoids on lymphocyte proliferation; natural killer (NK) cell killing activity; TNF-α, IFN-γ, and IL-2 concentrations in serum; and the spleen lymphocyte apoptosis of colitis mice." (PMID 33562018, 2021). "Although all mice receiving TNBS developed colitis, those receiving LD IL-2 exhibited reduced inflammation and injury compared to PBS (P < 0.001) that was similar to what we previously observed when CD4+ T cells were HLA restricted." (PMID 33717161, 2021). "The requirement of IL-2 for Th1 differentiation suggests that the regulation of T cell activation is a potent clinical strategy for colitis." (PMID 33669855, 2021). "Under these conditions, Tregs were able to suppress colitis; however, this was inhibited by administration of IL-2-REH." (PMID 34003116, 2021). "The secreted proinflammatory cytokines (IFN-γ, IL-2 and TNF-α) from immune cells result in loss of intestinal epithelial barrier integrity and magnify inflammatory response in colitis." (PMID 33808686, 2021). "ELISA confirmed that HYJJ administration inhibited the levels of IL-2, IL-10 as well as IL-12 in the serum collected from mice undergoing experimental colitis." (PMID 34122086, 2021).
colitis (continued). "In contrast, in plasma, colitis-induced increases in interleukin (IL)-2, leukemia inhibitory factor (LIF), monocyte chemoattractant protein (MCP)-1, and tumor necrosis factor (TNF) were reduced in animals with an A allele." (PMID 34916909, 2021). "Low-dose IL-2 has therapeutic effects on DSS-induced colitis and potential clinical value in treating UC." (PMID 33409535, 2021). "Reasoning that T cell activation is a component of inflammation in the intestine, we initially employed NSG mice expressing human HLA to assess LD IL-2 as a therapeutic to expand human Treg cells and suppress experimental colitis." (PMID 33717161, 2021). "Recently, we demonstrated that LD IL-2 was protective against experimental colitis in immune humanized mice in which human CD4+ T cells were restricted to human leukocyte antigen (HLA)." (PMID 33717161, 2021). "In this study, we demonstrated that low physiological concentrations of IL-2 ameliorated clinical disease activity in mice with DSS-induced colitis." (PMID 32308767, 2020). "Pathway enrichment analysis was performed for each cluster to identify significant pathways perturbed by DSS-induced colitis and restored by low-dose IL-2." (PMID 32308767, 2020). "The expression of iNOS, which is regulated by NF-κB, increased in DSS-induced colitis and was reduced by treatment with low-dose IL-2 back to the basal levels observed in the control group." (PMID 32308767, 2020). "Herein, we evaluated the therapeutic efficacy of low-dose IL-2 in dextran sulfate sodium (DSS)-induced experimental colitis in mice." (PMID 32308767, 2020). "Taken together, these results suggested that low-dose IL-2 reduced the signs of DSS-induced colitis in mice." (PMID 32308767, 2020). "Spleen cells from mice with colitis treated with tryptanthrin produce less IL-2 and IFN-γ after mitogen stimulation than those from untreated mice." (PMID 32938944, 2020). "Specifically, low concentrations of IL-2 reduced pro-inflammatory cytokine production in the colons of mice with DSS-induced colitis and improved intestinal barrier integrity." (PMID 32308767, 2020). "To better understand the treatment effects of IL-2 in mice with DSS-induced colitis, we performed RNA-seq analysis of the mouse colon samples obtained from the control, DSS+PBS, and DSS+IL-2 (16K IU/day)." (PMID 32308767, 2020). "The secretion of IL-2, IL-7, IL-12, and IL-15 in colonic tissues from colitis mice in the DSS group was higher than that in the normal, DSS + SSP, and DSS + 5-ASA groups." (PMID 32714185, 2020). "In conclusion, low-dose IL-2 effectively improved DSS-induced colitis symptoms in mice, resulting in the overall attenuation of histological changes, expression and secretion of pro-inflammatory cytokines, and immune cell infiltration." (PMID 32308767, 2020). "The low-dose IL-2 groups (16K IU/day and 32K IU/day) significantly improved the body weight in mice with colitis compared to the DSS+PBS group (P < 0.001)." (PMID 32308767, 2020). "To examine the effect of low concentrations of IL-2 in an experimental colitis model, we induced acute colitis in mice by adding 3% DSS to their drinking water for 7 days." (PMID 32308767, 2020). "We further identified 3,393 genes that overlapped between colitis-related and IL-2 treatment -related genes and the resulting heatmap was divided into five clusters." (PMID 32308767, 2020). "The results also showed that treatment with LP-YS4 significantly reduced the serum concentrations of ET-1, SP, and IL-10 while significantly increasing those of SS, VIP, and IL-2 in colitis mice (P < 0.05)." (PMID 32849906, 2020). "Gene expression of NF-κBp65 was upregulated in DSS-induced colitis and suppressed by low-dose IL-2 treatment (16K IU/day)." (PMID 32308767, 2020). "Together, these results show that low-dose IL-2 treatment alleviated the defective phenotypes of DSS-induced colitis to some degree at both the cellular and molecular levels in vivo." (PMID 32308767, 2020).
colitis (continued). "In this study, we aimed to determine the effects of low-dose IL-2 as a therapeutic for UC on dextran sulfate sodium (DSS)-induced colitis." (PMID 32308767, 2020). "Studies are necessary to investigate the direct effects of low-dose IL-2 on the intestinal epithelium in colitis in order to determine the appropriate dose of IL-2." (PMID 32308767, 2020). "In detail, B cell immunity is inoperative, either due to the lack of mature B cells (Rag1−/−), the disturbed proliferation and induction of Bregs (IL-2−/−), or the dysfunction of Bregs (IL-10−/−) in all three colitis mouse models." (PMID 32038631, 2019). "During acute colitis, the proportion of IL-2-producing CD11c+MHCII+ (CD64−F4/80−) DCs in LP-colon further increased." (PMID 29549257, 2018). "Deleting IL-2 in CD11chighMHCII+ cells induces spontaneous colitis resembling human inflammatory bowel disease." (PMID 29549257, 2018). "IL10 KO and IL2 KO mice spontaneously develop colitis when raised under conventional conditions by dysregulated immune responses against commensal bacteria." (PMID 30333822, 2018). "Hemizigosity in EP4 during T cell induced colitis in the adoptive T cell transfer colitis model is partially protective, and also affects IFNγ and IL2 production by MLN CD4+ cells." (PMID 30619314, 2018). "The GIT inflammation in Il2−/− mice is influenced by microbiotia as colitis is significantly reduced under germ-free conditions." (PMID 30662436, 2018). "In previous work we showed that the pathobiont E. coli mpk induces colitis in Il2−/− mice, whereas the symbiont B. vulgatus mpk maintains homeostasis." (PMID 30283451, 2018). "Here the authors use a mouse model of spontaneous colitis to show that calcineurin-NFAT-induced IL-2 production by dendritic cells regulates the balance between Treg and effector T cells in the gut lamina propria." (PMID 29549257, 2018). "In colonic tumorigenesis, the inflammatory cells contributed to the colitis by generating proinflammatory cytokines, such as IL-1α, IL-2, IL-6, TNF-α, INF-γ." (PMID 29162930, 2017). "In this analysis emergence of CTLA4 antibody induced colitis in patients treated with HD IL-2 following ipilimumab was seen, consistent with a prior report from the National Cancer Institute." (PMID 27660706, 2016). "Patients who had evidence of significant prior CTLA-4 related colitis should only be treated with HD IL-2 after endoscopic evaluation to ensure resolution of colitis." (PMID 27660706, 2016). "Here we report that HBO2 significantly reduces severity of DSS-induced colitis, as evidenced by the clinical features, histological assessment, impaired immune cell expansion and mobilization, and reversal of IL-1β, IL-2, and IL-6 gene expression." (PMID 27656047, 2016). "There have been prior reports of colitis and bowel perforation in patients receiving IL-2 therapy following ipilimumab." (PMID 27660706, 2016). "Our experiments demonstrated that high transcription level of IL-2 in colon tissues of untreated colitis mice were significantly down-regulated in ERC treated mice." (PMID 25475342, 2014). "This is due to TNBS-induced over expression of IL-12, IFN-γ and IL-2, which supports the study that inducible colitis is due to Th-type 1 response." (PMID 21527003, 2011). "Recently, it was shown that the induction of colitis in IL-2−/−-mice seems to be toll-like-receptor (TLR) independent, as IL-2−/− MyD88−/− TRIF−/− triple-deficient mice still developed colitis." (PMID 18545662, 2008). "Contributions of E. coli and other gut bacteria to the aggravation of colitis were shown earlier in mono-associated germ-free IL10-/- and IL2-/- mice and by the curative effects of antimicrobial therapy." (PMID 17653282, 2007). "Furthermore, the enhanced IL-2 signaling in the transferred Prdm1-knockout Treg cells likely contributed to the T cell–induced colitis by expanding the number or function of these poorly suppressive “effector” Treg cells." (PMID 40680114, 2025).
colitis (continued). "Predicted upstream regulators of ILCs in CPI-C included Tbx21, encoding the transcription factor T-bet, and genes encoding the cytokines Il2, Il18 and Il21, suggesting that ILC1 may contribute to colitis in this model." (PMID 39496592, 2024). "Furthermore, the probiotic formulation including Bifidobacterium and Lactobacillus reduced the severity of experimental colitis by inducing Treg cell population in MLNs, while concurrently increasing IL-2, IL-4, and IL-10 expression." (PMID 37110390, 2023). "Analysis of cytokines predicted to activate Ifng expressing CD4+ T cells in CPI colitis included IL2 (z score 4.7, P < 1.0 × 10−27), IL7 (z score 3.8, P < 9.8 × 10−19), IL15 (z score 3.4, P < 5.2 × 10−34), IL18 (z-score 2.0, P < 4.0 × 10−25) and IL23A (z-score 2.6, P < 2.1 × 10−31)." (PMID 37872166, 2023). "IL-2 is synthesized by T cells after being stimulated by antigens, inducing the expression of immune cells and exerting immune regulation functions, and reducing IL-2 can induce spontaneous colitis in mice." (PMID 35739900, 2022). "(10 g/kg, concentrated water decoction) could protect against the acetic acid and dinitrochlorobenzene-induced colitis in a rat model by regulating the levels of IL-2, IL-10, and IL-17 cytokines in serum." (PMID 36160392, 2022). "In the absence of IL2 expression in Rag1–/– × Rorc-Cre × Il2fl/fl mice, more severe colitis is induced upon adoptive transfer of naïve CD4+ T cells, compared with Rag1–/– × Il2fl/fl mice, demonstrating the relevance of ILC3-derived IL2 in modulating pathogenic T cells." (PMID 35618586, 2022). "In our study, the higher level of IL-2 determined in the jejunum may explain why the colon is prone to colitis and the jejunum is less inflammatory." (PMID 35739900, 2022). "In IL-2 knockout mice, B. vulgatus reportedly ameliorates E. coli-induced colitis development." (PMID 35693794, 2022). "Furthermore, mice that develop spontaneous colitis due to defects in IL-2, IL-10, or TGFβ have many effector and memory T cells with TCRs that in wild-type mice are found on colonic FOXP3+ cells." (PMID 34421921, 2021). "Thus, low-dose IL-2 exerts an anti-colitis effect by inhibiting the gene expression and secretion of pro-inflammatory factors." (PMID 32308767, 2020). "Based on our RNA-seq analysis results, mice with DSS-induced colitis treated with low-dose IL-2 exhibited the differential expression of a specific set of genes in the colon, in particular, those associated with the PI3K-AKT signaling pathway—compared to mice treated with PBS." (PMID 32308767, 2020). "Importantly, low-dose IL-2 was effective in ameliorating the disruption of epithelial barrier integrity in DSS-induced colitis tissues by restoring tight junction proteins and mucin production and suppressing apoptosis." (PMID 32308767, 2020). "In the DSS-induced colitis group, there were substantial reductions in zonula occludens-1 (ZO-1) and occludin mRNA levels; however, these recovered to the control levels in the low-dose IL-2 groups (16K IU/day and 32K IU/day)." (PMID 32308767, 2020). "Furthermore, the gene expression levels of PI3K-AKT were increased after treatment with certain concentrations of IL-2 in the mCOs isolated from DSS-induced colitis mice, consistent with a previous report that IL-2 signaling induces PI3K-AKT-mediated survival." (PMID 32308767, 2020). "DSS exposure resulted in a survival rate of 43.7%, whereas the survival rate of mice with DSS-induced colitis was significantly improved in the low-dose IL-2 groups (the survival rates for 16K IU/day and 32K IU/day recombinant IL-2-groups were 88.9% and 68.0%, respectively)." (PMID 32308767, 2020). "It was observed that LP-YS4 could increase the level of IL-2, thus regulating immunity and alleviating colitis." (PMID 32849906, 2020).